LINC00682 (long independently transcribed non-coding RNA 682)
Gene: Long non-coding RNA gene on chromosome 4 (41,872,738 to 41,882,955, reverse strand). Ensembl gene ENSG00000245870.
Diseases named in the same sentence as LINC00682 in open-access papers:
LINC00682 is named in the same sentence as 2 diseases in open-access papers, as found by Europe PMC text mining. Sharing a sentence is not in itself a finding about the gene and the disease. The quoted sentences say what the papers report.
cancer (1 paper, 2019). A tumor composed of atypical neoplastic, often pleomorphic cells that invade other tissues. "Results show that LINC00682 levels are significantly downregulated in cancer tissues (“Can”), when compared to those in the adjacent epithelial (“Epi”) tissues." (PMID 31822638, 2019).
LINC00682 also shares sentences with these, for which no sentence is quoted: hepatocellular carcinoma (1 paper).